IGFBP6 (insulin like growth factor binding protein 6)
Diseases named in the same sentence as IGFBP6 in open-access papers (continued):
Sharing a sentence is not in itself a finding about the gene and the disease.
glioma (11 papers, 2018 to 2026). A benign or malignant brain and spinal cord tumor that arises from glial cells (astrocytes, oligodendrocytes, ependymal cells). "The genes Lysyl Oxidase Like 1 (LOXL1) and Insulin Like Growth Factor Binding Protein 6 (IGFBP6) were consistently selected and linked to glioma survival, emphasising their clinical significance." (PMID 40428295, 2025). "Unlike other IGFBPs, the expression of IGFBP-6 inversely correlates with glioma grade and higher plasma IGFBP-6 levels have been associated with a better prognosis." (PMID 33604294, 2020). "LOXL1 and IGFBP6 have already been associated with glioma survival in the literature." (PMID 40428295, 2025). "Finally, elevated expression of IGF-1R and IGF2 in gliomas associated with poor patient survival and tumor expression levels of IGFBP6 directly correlated with overall survival time in patients with GBM." (PMID 30231881, 2018). "In addition, IGFBP6 is inversely associated with glioma grade and predicts better survival." (PMID 33282953, 2020). "Lactate has also been shown to regulate the polarization of glioma microglia by upregulating IGFBP6 expression." (PMID 41463052, 2025). "IGFBP6 is a potent apoptosis inducer in non-small-cell lung cancer cells and glioma cells, which has been shown to attract immune cells to the tumor microenvironment." (PMID 35884546, 2022). "IGFBP-6 also plays a crucial role in CAFs regulation, participating in epithelial–mesenchymal transition and contributing to glioma cell migration." (PMID 35457175, 2022). "Lastly, IGFBP-6 is a member of a paracrine signaling circuit involving the IGF-II-IGF-IR axis present in TMZ-resistant glioma cells." (PMID 33604294, 2020). "On the other hand, the TMZ-sensitive cells secreted high levels of IGFBP6, whereas IGFBP6 was almost undetectable in the supernatants of the TMZ-resistant glioma cells." (PMID 30231881, 2018). "In mice bearing intracranial human glioma xenografts, overexpression of IGFBP6 in TMZ-resistant cells increased survival." (PMID 30231881, 2018). "Our results do not however address the origins of heterogeneity, and leave open the issue of how amplified IGF2+/IGF-1R+ and IGFBP6+ subpopulations arise during the establishment of a glioma." (PMID 30231881, 2018). "We also examined the functional effect of TMZ-sensitive glioma cell-secreted IGFBP6 on TMZ-resistant cells." (PMID 30231881, 2018). "Taken together, these results indicate that IGFBP6 produced by TMZ-sensitive glioma cells can modulate IGF-1R/AKT signaling in TMZ-resistant cells." (PMID 30231881, 2018). "Furthermore, IGFBP6 has been found to, in turn, enhance the migration and colony-forming ability of glioma cells." (PMID 41463052, 2025). "IGFBP6 may serve as an independent prognostic factor for the prognosis of glioma patients, and overexpression of IGFBP6 can induce apoptosis of glioma cells." (PMID 37088808, 2023). "Specifically, Zong Z. and colleagues recently demonstrated that IGFBP-6 is an unfavorable prognostic factor in glioma, affecting tumor malignancy with an expression positively correlated with the immunosuppressive response in glioma patients." (PMID 35457175, 2022). "Finally, to evaluate the role of IGFBP6 in the progression of glioma cells in vivo, we engineered TMZ-resistant UTMZ glioma cells that stably overexpress and secrete IGFBP6 protein (top)." (PMID 30231881, 2018). "Using chemoresistant and chemosensitive wild-type and transgenic glioma cells, we further found that a paracrine mechanism driven by IGFBP6 secreted from TMZ-sensitive cells abrogates the proliferation of IGF-1R-expressing TMZ-resistant cells in vitro and in vivo." (PMID 30231881, 2018). "Furthermore, although higher plasma IGFBP6 levels have been associated with a better prognosis for GBM patients, the specific role of IGFBP6 in the development and progression of glioma was also unknown." (PMID 30231881, 2018).
glioma (continued). "Using the polymerase chain reaction, GBM cell lines were found to express mRNA for IGFBP genes: IGFBP-1 in 42%, IGFBP-2 in 65%, IGFBP-3 in 97%, IGFBP-4 in 3%, IGFBP-5 in 74%, IGFBP-6 in 94%, and IGFBP-7 in 87% of glioma cell lines." (PMID 35832140, 2022). "Here, we show that TMZ-resistant and TMZ-sensitive glioma cells co-exist within GBM tumors, and the interaction of these cells through the secretion of IGF2 and IGFBP6, respectively, regulates cell proliferation and growth of the tumor." (PMID 30231881, 2018). "Notably, genes such as LOXL1, IGFBP6, TNFRSF18 and MMP19, identified by both methods, have established links to glioma survival." (PMID 40428295, 2025). "We determined that in human glioma tissue, glioma cell lines, and patient-derived xenograft cell lines, treatment with TMZ enhances the expression of IGF1 receptor (IGF-1R) and IGF2 and decreases the expression of IGFBP6, which sequesters IGF2." (PMID 30231881, 2018). "Since TMZ-sensitive glioma cells produce IGFBP6, we evaluated the effects of conditioned medium from TMZ-sensitive U251 cells on IGF2-dependent phosphorylation of IGF-1R and AKT expressed by TMZ-resistant UTMZ glioma cells." (PMID 30231881, 2018).
rhabdomyosarcoma (9 papers, 2005 to 2020). A rare aggressive malignant mesenchymal neoplasm arising from skeletal muscle. "IGFBP6 encourages migration in rhabdomyosarcoma cells via mediating the MAP kinase signaling pathway, while IGFBP6 plays a suppressive role on tumor growth in ACTH-secreting pituitary adenoma through activation of the PI3K-AKT-mTOR signaling pathway." (PMID 33282953, 2020). "This antiangiogenic action of IGFBP-6 was demonstrated in vivo in a tumor model by transplanting human Rh30 rhabdomyosarcoma cells stably transfected with IGFBP-6 into BALB/c nude mice." (PMID 29686648, 2018). "In particular, IGFBP-6 (40 nM, 1 μg/ml) has been shown to induce chemotaxis in Rh30 rhabdomyosarcoma cells." (PMID 28977828, 2017). "IGFBP6 overexpression inhibits proliferation and promotes rhabdomyosarcoma cell apoptosis in vitro and dramatically inhibits xenograft growth in vivo." (PMID 27623076, 2016). "Most IGFBPs also have IGF-independent actions, and we have shown in recent years that IGFBP-6 inhibits angiogenesis as well as promoting migration of rhabdomyosarcoma and colon cancer cells in an IGF-independent manner." (PMID 25601855, 2014). "MAP kinase pathways are involved in IGFBP-6-induced rhabdomyosarcoma cell migration, so activation of these pathways was studied in HEY and SKOV3 cells." (PMID 25601855, 2014). "We previously showed that IGFBP-6-induced migration of rhabdomyosarcoma cells is dependent on activation of MAP kinase pathways." (PMID 25601855, 2014). "We have previously shown that MAP kinase pathways are involved in IGFBP-6-induced rhabdomyosarcoma cell migration, so we compared activation of these pathways in HEY and SKOV3 cells." (PMID 25601855, 2014). "In rhabdomyosarcoma cells, IGFBP-6 inhibited cell proliferation in a dose-dependent manner by inhibiting insulin-like growth factor II (IGF-II), which stimulates cell proliferation." (PMID 15846301, 2005). "IGFBP-6 inhibits the proliferation of rhabdomyosarcoma cell lines." (PMID 15846301, 2005). "Also, IGFBP-6 promotes migration of Rh30 rhabdomyosarcoma cells via a distinct pathway involving an unknown receptor." (PMID 28977828, 2017). "Furthermore, IGFBP-6 inhibited the proliferation of rhabdomyosarcoma cells." (PMID 15846301, 2005). "The findings of this study showed that IGFBP-6 increased migration of SKOV3 ovarian cancer cells in an IGF-independent manner, which is similar to our previous findings in rhabdomyosarcoma and colon cancer cells." (PMID 25601855, 2014). "Further, we have previously found that Akt was not involved in IGFBP-6-induced rhabdomyosarcoma cell migration." (PMID 25601855, 2014). "Moreover, IGFBP-6 expression has been previously associated with nonproliferative states and inhibition of IGF-2 dependent tumor cell growth in rhabdomyosarcoma, neuroblastoma, and colon cancer." (PMID 29387091, 2017). "In RD rhabdomyosarcoma and LIM 1215 colon cancer cells, mutant IGFBP-6 that does not bind to IGF-2 induces cellular migration, suggesting an IGF-independent function of IGFBP-6." (PMID 30911300, 2019). "In RD rhabdomyosarcoma cells, IGFBP-6 transiently increased phosphorylation of p38 MAPK, whereas ERK was constitutively activated and IGFBP-6 had no further effect." (PMID 25601855, 2014).
colon cancer (7 papers, 2014 to 2023). "The same authors also reported a promotion of LIM 1215 colon cancer cell migration stimulated by IGFBP-6, which leaves the final conclusion on the role of IGFBP-6 in colon cancer still to be assessed." (PMID 36013453, 2022). "Increased IGFBP6 levels were observed in the serum of aging mice and humans or in senescence induced by doxorubicin in colon cancer or by hydrogen peroxide in fibroblasts." (PMID 28572803, 2017).
myelofibrosis (7 papers, 2021 to 2025). A partial or complete replacement of the bone marrow stroma by fibrous tissue. "In primary myelofibrosis, IGFBP-6 has been implicated in the activation of the Sonic Hedgehog (SHH)/Toll-like receptor 4 (TLR4) axis, promoting stromal reprogramming and fibroblast proliferation." (PMID 40723309, 2025). "We recently demonstrated that IGFBP-6/SHH/TLR4 axis is implicated in alterations of the primary myelofibrosis microenvironment and that IGFBP-6 may play a central role in activating SHH pathway during the fibrotic process." (PMID 36836615, 2023). "In conclusion, our results suggest that the IGFBP-6/SHH/TLR4 axis is implicated in alterations of the primary myelofibrosis microenvironment and that IGFBP-6 may play a central role in activating SHH pathway during the fibrotic process." (PMID 34905501, 2021). "IGFBP-6 expression is increased in myelofibrosis, and IGFBP-6-induced myofibroblast differentiation is associated with an upregulation of cancer-associated fibroblast markers." (PMID 41226289, 2025). "IGFBP-6 expression levels vary across different fibrotic conditions, including dermal, renal, hepatic, cardiac fibrosis, and myelofibrosis." (PMID 40723309, 2025). "Several works demonstrated that IGFBP-6 is differentially expressed in dermal, renal, hepatic, cardiac fibrosis, and myelofibrosis." (PMID 35457175, 2022). "Future additional studies are now warranted to further dissect IGFBP-6 functional role in myelofibrosis." (PMID 34905501, 2021). "We observed a significant increase in IGFBP-6 expression levels in primary myelofibrosis patients, coupled with a reduction to near-normal levels in primary myelofibrosis patients with JAK2V617F mutation." (PMID 34905501, 2021). "The present study aims to investigate the involvement of IGFBP-6/sonic hedgehog /Toll-like receptor 4 axis in the microenvironment alterations of primary myelofibrosis." (PMID 34905501, 2021).
ovarian carcinoma (6 papers, 2014 to 2022). A malignant neoplasm originating from the surface ovarian epithelium. "The IGF system is implicated in ovarian cancer, so we studied the effects of IGFBP-6 in ovarian cancer cells." (PMID 25601855, 2014). "In conclusion, this study has shown differential effects of IGFBP-6 on migration of two ovarian cancer cell lines." (PMID 25601855, 2014). "PD98059, an inhibitor of ERK1/2 activation, and SP600125, a JNK inhibitor, were used to study the roles of MAPK pathways in IGFBP-6-induced ovarian cancer cell migration." (PMID 25601855, 2014). "In the Yang study, they proved that IGFBP-6 may have profound effects on the migration of two ovarian cancer cell lines, which may help in developing an IGFBP-6-based therapeutic for ovarian cancers." (PMID 35646648, 2022). "In ovarian cancer cell lines, differential effects of IGFBP6 on migration were observed." (PMID 27623076, 2016). "Small studies of IGFBP-6 in serum of patients with ovarian cancer are inconsistent, which may reflect methodological differences." (PMID 25601855, 2014). "IGFBP-6 is commonly expressed at low levels in ovarian cancers." (PMID 25601855, 2014). "However, IGFBP‐6 inhibited migration of HEY ovarian cancer cells (aggressive phenotype)." (PMID 30117676, 2018). "However, in contrast to these cell lines, IGFBP-6 inhibited migration of HEY ovarian cancer cells." (PMID 25601855, 2014). "Delineating the pathways underlying the differential effects on migration will increase our understanding of ovarian cancer metastasis and shed new light on the IGF-independent effects of IGFBP-6." (PMID 25601855, 2014). "The aim of this study was to determine the effects of IGFBP-6 on migration of HEY, SKOV3, and OVCAR-3 ovarian epithelial cancer cells, which, respectively, represent aggressive, transitional, and less aggressive tumors." (PMID 25601855, 2014). "A single microarray study showed that IGFBP-6 mRNA levels were lower in ovarian cancer tissue compared with non-cancerous tissue; this may reflect derepression of IGF-II action by decreased IGFBP-6, but levels were not confirmed in an independent assay." (PMID 25601855, 2014).
colorectal cancer (5 papers, 2021 to 2024). A primary or metastatic malignant neoplasm that affects the colon or rectum. "In colorectal cancer, low IGFBP6 expression is associated with poor survival." (PMID 37088808, 2023). "And preliminary experiments were conducted to verify that IGFBP2 and IGFBP6 were lowly expressed in gastric cancer, while IGFBP6 was lowly expressed in colorectal cancer." (PMID 40625452, 2024). "The qRT-PCR experiments verified the lower expression of IGFBP2 and IGFBP6 in gastric cancer and the lower expression of IGFBP6 in colorectal cancer." (PMID 37088808, 2023). "We observed in our study the highest IGFBP-1, IGFBP-2 and IGFBP-3 mRNA expression in Dukes’ stage D colorectal cancer cells, having the lowest level IGFBP-6." (PMID 34290976, 2021). "In light of previous scientific inquiries, it’s compelling to mention that many of the genes within this list of 10, specifically CAV1, DAPK1, GPX3, IGFBP6, TIMP1, GADD45B and ENO2 have been found associated intimately with colorectal cancer, as documented by several research studies." (PMID 38501104, 2024). "Besides, the qRT-PCR experiment confirmed the low expression of IGFBP2 and IGFBP6 in gastric cancer and the low expression of IGFBP6 in colorectal cancer." (PMID 37088808, 2023). "Interestingly, a recent study showed in vitro a dose-dependent inhibitory role of IGFBP-6 on proliferation, invasion and migration of colorectal cancer cells." (PMID 34290976, 2021).
nasopharyngeal carcinoma (5 papers, 2016 to 2024). A carcinoma arising from the nasopharyngeal epithelium. "Overexpression of IGFBP‐6 significantly suppressed the proliferation, invasion and metastatic activity of nasopharyngeal carcinoma cells and increased their apoptosis, indicating that IGFBP‐6 as a putative tumour suppressor gene." (PMID 30117676, 2018). "IGFBP6 showed its ability to bind the EGR1 promoter and induce its activity in stably transfected nasopharyngeal cancer (NPC) cell lines overexpressing IGFBP6." (PMID 34149804, 2021). "This study assessed the impact of IGFBP6 on the progression of nasopharyngeal carcinoma (NPC)." (PMID 27623076, 2016).
Obesity (5 papers, 2021 to 2024). Accumulation of substantial excess body fat. "A previous study showed that Igfbp6 was expressed at lower levels in obesity and was positively correlated with leptin, glucagon-like peptide 1 and cholecystokinin." (PMID 36209126, 2022). "Overall, systemic CCL5, GDF15, and IGFBP6 levels declined following 12 months of anti-obesity therapy and weight loss, irrespective of a conservative or bariatric approach." (PMID 36430499, 2022). "We found numerous correlations between IGFBP6 concentration and obesity metabolic parameters." (PMID 34371941, 2021). "The data in literature about the role of IGFBP6 in obesity in children are scarcely available." (PMID 34371941, 2021). "It seems that a decreased level of IGFBP6 might play some role in obesity in the child population." (PMID 34371941, 2021). "We speculate that the low level of IGFBP6 in obese patients cannot decrease the level IGF2 and that may be the factor that contributes to obesity." (PMID 34371941, 2021).
rheumatoid arthritis (5 papers, 2017 to 2025). A chronic, systemic autoimmune disorder characterized by inflammation in the synovial membranes and articular surfaces. "Emerging evidence from rheumatoid arthritis, heat-stressed DCs, and cystic fibrosis models suggests context-dependent immune modulation, though IGFBP6’s sepsis-specific mechanisms were previously uncharacterized, to our knowledge." (PMID 40892465, 2025). "In rheumatoid arthritis patients, IGFBP6 was shown to be able to induce high levels of T-lymphocyte migration in vitro." (PMID 35832140, 2022). "A similar report also confirmed the chemotactic role of IGFBP6 in rheumatoid arthritis." (PMID 37069938, 2023). "IGFBP-6 was found at higher levels in sera and synovial tissue of rheumatoid arthritis patients." (PMID 35903151, 2022). "Recently, insulin-like growth factor binding protein 6 (IGFBP-6) has been shown to play a putative role in the immune system and was found at higher levels in the sera and synovial tissue of rheumatoid arthritis patients." (PMID 35903151, 2022).
Stroke (5 papers, 2010 to 2025). Sudden impairment of blood flow to a part of the brain due to occlusion or rupture of an artery to the brain. "Meanwhile, elevated levels of IGFBP 6 in blood at admission have been linked to higher possibility of early neurologic improvement after stroke." (PMID 40048365, 2025). "Our finding indicated that baseline serum CRP, GDNF, IFN-γ, IGFBP-6, IL-4, LYVE-1, MMP-2, PAI-1, and PDGF-AA levels were associated with post-thrombolytic sICH in stroke." (PMID 35173671, 2022). "Also, it is interesting that four of the eleven top-ranked proteins for association with stroke risk are members of the IGF signaling pathway (IGFBP4, IGF2, IGFBP6, IGFBP2)." (PMID 20667078, 2010). "For stroke, positive correlations of B2M with each of IGFBP2, IGFBP4, and IGFBP6 were also evident at baseline and year 1 in both treatment groups, and both trials." (PMID 24373343, 2013). "In addition to these, certain other IGF binding proteins are evidently influenced by hormone therapy and may be related to CHD (IGFBP1) or stroke (IGFBP2, IGFBP6)." (PMID 20667078, 2010).
atherosclerosis (4 papers, 2022 to 2026). A disease characterized by the build-up of fatty material and calcium deposition in the arterial wall resulting in partial or complete occlusion of the arterial lumen. "Elevated levels of IGFBP-6 in circulation and tissues have been observed in conditions such as atherosclerosis, suggesting that IGFBP-6 might contribute to the remodeling process in PAH." (PMID 41169887, 2025).
gastric cancer (4 papers, 2021 to 2024). A primary or metastatic malignant neoplasm involving the stomach. "IGFBP1/5/7 expression was significantly associated with overall survival whereas IGFBP6/7 expression was significantly correlated with disease-free survival in gastric cancer patients." (PMID 34745945, 2021). "In gastric cancer (GC) samples Uc.416+A is highly expressed compared to non-cancer gastric mucosa, inversely with the expression of its putative target IGFBP-6 which is low in GC." (PMID 35597813, 2022). "A study of 11 gastric cancer cell lines demonstrated that IGFBP1 expression levels were extremely low in all cell lines, whereas IGFBP2 and IGFBP4 were expressed in 10 and 9 cell lines, respectively, and IGFBP3, IGFBP5, and IGFBP6 were expressed in half of all cell lines." (PMID 34745945, 2021).